MICB (MHC class I polypeptide-related sequence B)
Diseases named in the same sentence as MICB in open-access papers (continued):
Sharing a sentence is not in itself a finding about the gene and the disease.
tumor (continued). "We coupled the MICAB1-Fc silent mAb to potent DNA binder payloads, to promote the killing of MICA/MICB-expressing tumor cells." (PMID 35967081, 2021). "Other studies demonstrate that miR-10b inhibits NK cells to recognize and attack to cancer cells through targeting MICB, a ligand expressed by tumor cells and recognized by NKG2D receptor of NK cells." (PMID 34179081, 2021). "Activating receptor NKG2D on the surface of NK cells and stressing-inducing ligand MICA and MICB on tumor cells can all be induced by HDAC inhibitors to increase NK cell killing of tumor cells." (PMID 34579759, 2021). "Eventually, the downregulation of MICB expression enables the tumor to avoid immune recognition which explains the reason of a worse OS in low MICB patients with CRC." (PMID 32306128, 2020). "We implanted B16-sMICB tumor cells via lateral tail vein injection into syngeneic male MICB transgenic mice." (PMID 32517713, 2020). "The NKG2D form transduces activating signals to initiate cytotoxic activity upon binding to specific stress-induced ligands, MICA and MHC class I polypeptide-related sequence B (MICB), which are selectively expressed on tumor cells." (PMID 33396603, 2020). "NK cells mainly identify tumor cells and initiate the killing process by recognizing MICA/MICB on tumor cells through the NKG2D receptor." (PMID 31980023, 2020). "We recently discovered that tumor cell-associated NKG2DL, predominantly MICA and MICB, were cleaved following interaction with platelets or platelet releasate." (PMID 33424862, 2020). "A recent study demonstrated that antibodies targeting MICA and MICB can prevent NK cell recognition and tumor cell binding, inhibiting tumor growth in fully immunocompetent mouse models as well as humanized mouse models." (PMID 32762681, 2020). "miR-BART2-5p maintains tumor cell survival by downregulating the major histocompatibility complex (MHC) class I polypeptide-related sequence B (MICB) recognized by the natural killer group 2 member D receptor present on NK cells." (PMID 32194570, 2020). "MiR-10b upregulated in tumor cells suppresses NK-mediated killing of tumor cells via targeting stress-induced cell surface molecule MICB." (PMID 33321819, 2020). "The interaction between NKG2D on the NK cell and NKG2DL (MICA and MICB) on the tumour cell activates NK cell anti-tumour functions." (PMID 30908480, 2019). "Initially, we confirmed that the axis is functional in NK targeting of our cell lines by NK cell functional assays in the presence/absence of neutralising antibodies to NKG2D and the MICA and MICB tumour expressed ligands." (PMID 30908480, 2019). "As a consequence, MICA and MICB are upregulated, which improves tumor cell recognition by innate immune effectors and thus the sensitivity to natural killer cell-mediated killing." (PMID 31805711, 2019). "In terms of cancer therapy, it is well appreciated that MICA and MICB are abundantly expressed in human tumours." (PMID 30626155, 2019). "The expression of surface MICA and MICB was markedly reduced for each epithelial cancer cell line when cloaked with tumour cells." (PMID 30908480, 2019). "For instance, AR42 and panobinostat provoke an upregulation of MHC class I/II and of MICA/MICB on tumor cells, an increase in tumor infiltration by T cells and a decrease in the number of immunosuppressive MDSC." (PMID 31805711, 2019). "NK cells that were pre-treated with recombinant MICA and MICB had decreased anti-tumour functions compared with the IgG-Fc control protein." (PMID 30908480, 2019). "For example, the antibodies, stabilizing MICA and MICB on the surface of tumor cells, were proved to enhance the cytotoxicity of NK cells." (PMID 31288857, 2019). "More recently, Ab-based inhibition of MICA and MICB shedding promoted anti-tumour immunity through the activation of NK cells through dual stimulation of the NKG2D and CD16 Fc receptor pathways." (PMID 30626155, 2019).
tumor (continued). "A number of microRNAs can quench the tumor response by suppressing the MHC class 1-related chain molecule A and B (MICA and MICB), which are expressed on tumor cells and are ligands of the natural killer (NK) cell activating receptor NKG2D." (PMID 30046565, 2018). "On the other hand, downregulation of NK-activating ligands for NKG2D such as MICA and MICB and increased shedding of tumor-derived soluble MIC also impair NKG2D-mediated NK cell tumor recognition." (PMID 28620386, 2017). "Major histocompatibility complex class I chain-related proteins A and B (MICA and MICB) are important ligands for recognition of tumor cells by immune effector cells." (PMID 29029468, 2017). "MHC class I chain related-proteins A (MICA) and B (MICB) are natural killer group 2D ligands that mediate tumor surveillance." (PMID 29221214, 2017). "It has been reported that MICA and MICB are heat-induced, and that excessive soluble MICA and MICB in cancer patients (shed by the tumor cells) and in pregnant women (shed by the fetal trophoblast) cause downregulation of NKG2D and relative immune suppression." (PMID 26745675, 2016). "It has been demonstrated in several reports that MICA or MICB proteins are shed by tumor cells in many types of cancers with potential prognostic value." (PMID 26909604, 2016). "As membrane-bound MIC can stimulate anti-tumor immunity, in order to eliminate experimental variation, we chose to develop these tumor models using the soluble form of MICB instead of membrane-bound MIC." (PMID 26625316, 2016). "In contrast, NZ28 significantly reduced the MICA and MICB membrane expression (MFI) in both tumor cell lines." (PMID 25854583, 2015). "CXCL9 was also induced in the metronomic CPA-treated tumor cells in association with other extracellular immune activators: TNFSF4, MICB, interleukins IL12, IL15, IL23, and IL17RB, and interferon response genes." (PMID 25952672, 2015). "Nine additional cellular miRNAs capable of targeting MICB were also discovered by our group and similarly to miR-10b, several of them (such as miR-373 and miR-93) were also shown to be involved in tumor metastases." (PMID 25426550, 2014). "Our results revealed that the weak expression of MICA and MICB was correlated with worse tumor differentiation, later TNM stage, and more lymphatic invasion." (PMID 24885711, 2014). "In vitro, both drugs induce ULBP1 and MICB on cell lines and primary tumor cells when incubated with either decitabine or 5-azacytidine." (PMID 24715892, 2014). "The MHC class I chain-related sequence A (MICA) and the MHC class I chain-related sequence B (MICB) are well-characterized NKG2DLs, and play an important role in NK cell-mediated anti-tumor immune responses." (PMID 24885711, 2014). "It was previously reported that VPA enhances NK cell-mediated cytotoxicity in myeloma, ovarian, and liver cancer cells by increasing the expression of MICA and MICB; however, the mechanisms responsible for this effect vary depending on the tumor type." (PMID 24885711, 2014). "Recent studies showed that the increase of MICA and MICB expression on target tumor cells induced an increase in sensitivity to lysis by NK cells." (PMID 23493799, 2013). "In the case for TSA, the mechanisms for this tumour cytotoxicity were associated with increased histone H3 acetylation and reduced HDAC1 expression at the MICA and MICB promoters regions." (PMID 22461998, 2012). "It prevents MICB detachment and inhibits tumor cells from evading immune monitoring." (PMID 41516373, 2026). "In vivo, Anti-MICB-CAR-NK cells exhibited a substantial inhibitory effect on tumor growth." (PMID 41516373, 2026). "Flow cytometry and CCK8 were utilized to study Anti-MICB-CAR-NK on tumor cell viability." (PMID 41516373, 2026). "Therefore, it is imperative to utilize MICB tumor targets to stimulate the activation of additional immune cells within the body, thereby initiating an attack on the tumor cells." (PMID 41516373, 2026).
tumor (continued). "This strategy can be used to target stress-induced ligands like MICA and MICB on tumor cells." (PMID 40226616, 2025). "MMPs or ADAMs can hydrolyze MICA and MICB on the surface of tumor cells into soluble molecules." (PMID 40563539, 2025). "Moreover, in colon carcinoma and sarcoma cells, treatment with HDAC inhibitor Entinostat, a class I HDAC1 and HDAC3 inhibitor, led to increase in expression of NKG2D ligand MICA and MICB, enhancing cytotoxicity of NK cells against tumor cells." (PMID 39161385, 2024). "Due to tumor cells’ cleavage of the MICB from the cell membrane for immune escape leading to progression and poor prognosis, we hypothesize that targeting sMICB could be a basis for new therapeutic approaches for these patients." (PMID 38139416, 2023). "However, xenograft-derived tumor cells lost Fas, MICB, and ICAM-1 expression, and downmodulated HMGCR, the rate-limiting enzyme of the mevalonate pathway producing pAgs." (PMID 37139603, 2023). "MICA/MICB are transmembrane glycoproteins that, in tumor evasion, undergo proteolytic shedding and function as a soluble decoy preventing activation through cell-membrane binding by quenching NKG2D, a receptor that, during cellular stress, gets activated and leads to cytotoxicity." (PMID 36968223, 2023). "Furthermore, preserving the anti-tumour activity of T cells and NK cells in MHC-I deficient tumours is achievable through a vaccine approach that targets MICA and MICB stress proteins." (PMID 37454231, 2023). "Treatment of colon carcinoma cells with entinostat led to enhancement of acetylated histone 3 (AcH3) binding to MICA and MICB promoters, increasing their expression in a dose and time-dependent manner, resulting in higher NK cell-mediated tumor cell lysis, as compared to untreated cells." (PMID 37090711, 2023). "Because the presence of MICA and MICB on tumor exosomes has been validated, thus it is likely that exosomal MICA/B might be able to alter NKG2D expression similar to their soluble counterparts." (PMID 35031075, 2022). "Similar to the NKG2D ligands MICA and MICB, the NKp30 ligand B7-H6 could be cleaved from the surface of tumor cells and released as soluble B7-H6, thus preventing the NKp30-mediated recognition of tumor cells." (PMID 34203391, 2021). "Important membranous MICA/MICB staining was observed in tumor biopsies at various scores." (PMID 35967081, 2021). "Furthermore, MICA and MICB shedding from a range of tumour cell lines was attributed to either or both ADAM10 and ADAM17, but the regulation of this process was different depending on the cancer cell lines tested." (PMID 33352921, 2020). "High MICB expression was significantly associated with non-mucinous histological type (P < 0.001) and tumor size ≤ 4.0 cm (P = 0.001)." (PMID 32306128, 2020). "Interestingly, Schrambach and colleagues revealed MICA and MICB mRNA transcripts in healthy organ tissue as well as various tumours, suggesting regulation of surface NKG2DL expression is not solely controlled at a transcriptional level." (PMID 33352921, 2020). "Given that MICA and MICB are lost from the tumour cell surface in a platelet-dependent manner, we hypothesised a role for the platelet in promoting the release of soluble NKG2D ligands into the microenvironment of the cloaked tumour cells." (PMID 30908480, 2019). "In this study, we report that platelet cloaking of tumour cells promotes the loss of the NKG2D ligands, MICA and MICB, from the surface of tumour cells, inducing their secretion into the tumour microenvironment where they suppress NKG2D receptor expression on NK cells." (PMID 30908480, 2019). "In addition, metastasis-associated microRNA miR-10b (also known as metastamir), which promotes tumor invasion and metastasis by targeting multiple genes, downregulates MICB expression by binding directly to the 3′-UTR of MICB." (PMID 29973929, 2018).
tumor (continued). "In part, these miRNAs were shown to be overexpressed in the tumor itself (“oncomiRs”), like miR-93 that targets both MICA and MICB, but also in metastasis-associated miRNAs (“metastamiRs”), like miR-10b, that targets MICB expression." (PMID 30254634, 2018). "The data showed a decreased number of CD56dim NK cells in the peripheral blood of SS patients, impaired expression of NK-activating receptors, such as NKG2D and NKG2C, and expansion of “memory” CD57+NKG2C+ NK cells, together with increased sMICA/MICB, which acts as tumor escape mechanism." (PMID 29190907, 2017). "Thus, the upregulation of MICA and MICB by resveratrol promotes the immune recognition and clearance of tumor cells in vivo." (PMID 29029468, 2017). "Furthermore, we evaluated by ELISA the presence of soluble MICA (sMICA) or MICB (sMICB) in tumor cell supernatants following treatment with the CAFs CMs." (PMID 28423623, 2017). "The mechanism underlying the enhanced tumor cell killing may involve the increased expression of MICA, MICB, PVR, and Nectin-2 proteins on MM cells and the ligands of the activating receptors, NKG2D and DNAM-1." (PMID 27992381, 2017). "As tumor cells also express MICB, the ebv—miR—BART2-5p, may be in this way involved in GBM progression." (PMID 25950799, 2015). "However, when they were crossed with the TRAMP mice that develop spontaneous prostate tumors, TRAMP/MICB mice exhibited expedited tumor progression in comparison to TRAMP littermates whereas TRAMP/MICB.A2 mice enjoyed tumor-free survival." (PMID 25788898, 2015). "This hypothesis is supported by several studies which demonstrate that MICB was not only expressed in tumor cells but also in different non-tumor cell lines under stress conditions." (PMID 25626490, 2015). "We previously demonstrated that miR-10b is not only involved in tumor promotion and metastases, but also in immune escape, as we showed that miR-10b is capable of targeting MICB, a stress-induced ligand that is recognized by the potent NK activating receptor NKG2D." (PMID 25426550, 2014). "Interestingly, several of the ten MICB-targeting microRNAs, such as miR-10b, are involved in tumor formation and metastasis." (PMID 25426550, 2014). "Moreover, MICA and MICB appeared to act as a tumor-growth factor resulting in strong tumor proliferation in dose-dependent induction." (PMID 22899948, 2012). "Moreover, TSA, SAHA, VPA, and sodium butyrate were also found to increase the expression of the MHC class I-related chain A (MICA) and chain B (MICB) on tumour cells." (PMID 22461998, 2012). "We can further speculate that malignant cells not only can deplete MICA and MICB in situ to avoid immune recognition, but they can also use the stress factors as endogenous tumor growth factors." (PMID 21477352, 2011). "However, MICA and MICB can be cleaved from tumor cells by tumor-associated mellatoproteinases, which leads to soluble MICA and MICB that can downregulate the expression of NKG2D." (PMID 20350313, 2010). "Blocking the hydrolytic shedding of MICB may have promoted the secretion of perforin and granzyme B, leading to more NK cell infiltration of the tumor, which correlates with the activation of immune anti-tumor by MICB binding to ligand NKG2D." (PMID 41516373, 2026). "The Anti-MICB-CAR-NK possesses two key highlights: First, it secretes a free Anti-MICB-scFv fragment, which prevents the shedding of MICB from the tumor cell surface and may thereby activate immune cells such as T cells, γδT cells, and NK cells to attacking the tumor." (PMID 41516373, 2026). "Based on our hypothesis that shedding of stress-induced ligands on tumor cells generates peptide remnants, which may function as targetable neoepitopes, we generated antibodies against an MICB-derived octapeptide with prevalence in malignant and stressed cells." (PMID 41050431, 2025). "MICB‐vax also could induce immunological memory to prevent tumor recurrence." (PMID 38882209, 2024).
tumor (continued). "Additionally, upregulated antigen-presenting machinery comprising TAP1, TAP2, and MICB suggested that the cytotoxic T cells could be selectively programmed against tumor cells." (PMID 35884843, 2022). "In addition to PD-L1 upregulation, suppression of NK group 2D (NKG2D)-activating ligands (including ULBP1, ULBP2, ULBP3, MHC class I chain-related molecules A and B, MICA and MICB) may represent another way of tumor escape from NKCC." (PMID 34830209, 2021). "But tumor cells under antibody-dependent cell-mediated cytotoxicity might develop evasive pathways to avoid NK cell attack.Shedding is a good way for cancer cells to remove or avoid the surface expression of ligands such as MICB with the presence of metalloproteases in the tumor microenvironment." (PMID 32306128, 2020). "Moreover, in accordance with previous evidence indicating that NKG2D and DNAM-1 ligand are expressed on tumor cells with senescent phenotype upon treatment with genotoxic agents, we found a preferential expression of MICB on axitinib-treated senescent A-498 RCC cells." (PMID 26474283, 2015). "We found that ectopic MICA and MICB could induce a strong proliferative response on those cells, suggesting the possibility of an autoregulatory mechanism by which MICA and MICB secreted by the tumor cells are recognized by their own NKG2D receptor to contribute to tumor cell proliferation." (PMID 21477352, 2011). "Anti-MICB-CAR-NK and PANC-1 tumor cells were treated with 1:1, 1:2, 1:4 potency-to-target ratio cells for 24 h." (PMID 41516373, 2026). "As the expression of MICB protein by tumor cell lines increased, Anti-MICB-CAR-NK cells exhibited a stronger capacity to kill tumor cells, thereby demonstrating a clear MICB expression-dependent growth inhibition of tumor cells Anti-MICB-CAR-NK." (PMID 41516373, 2026). "All these experimental results on the PANC-1 xenograft model further confirmed the anti-tumor efficacy of Anti-MICB-CAR-NK and the possible anti-tumor mechanism." (PMID 41516373, 2026). "In animal models, the MICB vaccine significantly increased the enrichment of CD8+ T cells (17.9-fold) and NK cells (38.9-fold) within the tumor, creating a synergistic attack by immune cells." (PMID 41516373, 2026). "We demonstrated the successful expression of Anti-MICB-CAR in NK cells, which enhances the anti-tumor activity of NK cells both in vitro and in vivo." (PMID 41516373, 2026). "Anti-MICB-scFv and IL-15 in the supernatant of Anti-MICB-CAR-NK cells co-treated tumor cells with NK cells also promoted tumor cell killing compared to NK." (PMID 41516373, 2026). "Metalloproteinases hydrolyze MICA and MICB on the surface of tumor cells to generate soluble MICA and MICB (sMICA and sMICB)." (PMID 40563539, 2025). "The regulation of MICA and MICB by HIF-1α and metalloproteinases is of great significance for understanding tumor progression and molecular targeting." (PMID 40563539, 2025). "ULBP2, like MICA and MICB, is a human NKG2D ligand, and its ectopic expression in murine tumor cells carries the potential for immune rejection due to its xenogeneic nature." (PMID 40243581, 2025). "The COAD tumor samples showed an increase between 4.5 and 11.3-fold for ULBP1/2/3/6 compared to normal tissues, and MICA and MICB had expression increases of 1.29 and 1.89-fold." (PMID 40013140, 2025). "For example, IMP3 suppressed the NKG2D ligand UL16-binding protein 2 (ULBP2) and indirectly downregulated MHC class I polypeptide-related sequence B (MICB), which facilitated tumour immune evasion." (PMID 39718205, 2025). "NK cells rely on S-palmitoylation to enhance receptor-ligand interactions within lipid rafts, such as NKG2D-MICA/MICB and 2B4-CD48, facilitating tumor cell recognition and cytotoxicity." (PMID 40335986, 2025). "Multiple metalloproteinases hydrolyze MICA and MICB and convert them into soluble ligand molecules that inhibit NKG2D signal activation and impede the killing of tumor cells by NK cells and CD8+ T cells." (PMID 40563539, 2025).